RN7SL743P (RNA, 7SL, cytoplasmic 743, pseudogene)
Gene: Miscellaneous RNA gene on chromosome 16 (8,683,254 to 8,683,551, forward strand). Ensembl gene ENSG00000243954.
Homologues: Orthologues: chimpanzee Metazoa_SRP (97% identical), macaque Metazoa_SRP (91% identical). Paralogues in human: RN7SL1 (85% identical), RN7SL2 (85% identical), RN7SL3 (85% identical), RN7SL769P (83% identical), RN7SL448P (82% identical), RN7SL481P (82% identical), RN7SL122P (82% identical), RN7SL679P (82% identical), Metazoa_SRP (82% identical), RN7SL627P (82% identical), RN7SL7P (82% identical), Metazoa_SRP (81% identical), and 706 more.